DRD2 (dopamine receptor D2)
Diseases named in the same sentence as DRD2 in open-access papers (continued):
Sharing a sentence is not in itself a finding about the gene and the disease.
Obesity (113 papers, 2002 to 2026). Accumulation of substantial excess body fat. "Regarding the DRD2 gene, a higher obesity BMI was associated with the InsIns genotypes in DRD2rs1799732." (PMID 37631349, 2023). "Treatment with second-generation antipsychotics (SGAs) can cause obesity and other cardiometabolic disorders linked to D2 receptor (DRD2) and to genotypes affecting dopaminergic (DA) activity, within reward circuits." (PMID 37631349, 2023). "It is therefore possible to that the decrease in DRD2 predispose to search for reinforces, either drug in drug-addicted subjects or food in patients with obesity, to temporarily compensate for a decreased sensitivity of DA rereward circuits." (PMID 35369087, 2022). "DRD2 variants rs6276 and rs6277 reduce D2R expression/activity, reduced D2R expression/activity is associated with hypertension and related diseases, such as obesity and metabolic syndrome." (PMID 36359330, 2022). "Conversely, human obesity is associated with decreased dopamine signaling and dopamine receptor 2 (Drd2) expression in striatal regions, while acute loss-of-function models of Drd2 in rodents potentiate weight gain and increased consumption of palatable food." (PMID 36345942, 2022). "This raises the expectation that functional variants of the DRD2 gene are associated with overeating and the development of obesity disorders." (PMID 35893053, 2022). "On the genetic level, polymorphisms in the D2 receptor gene (DRD2) have been implicated in its association to obesity, as well as the weight gain response to antipsychotics." (PMID 30881281, 2019). "Other studies tend to investigate the association of another genetic variant that modulates the density of DRD2—DRD2/ANKK1-TaqIA SNP—with both obesity and addictive disorders instead, which is out of the scope of this review." (PMID 28615046, 2017). "For example, reduced dopamine function, particularly DRD2 signaling, is associated with obesity development in rodents and humans." (PMID 28588553, 2017). "Another gene involved in weight gain is the DRD2 gene, which encodes the dopamine D2 receptor and is associated with obesity." (PMID 26880915, 2016). "Individuals with at least one copy of the drd2 Taq1A allele have reduced brain D2R availability of ~30–40% and an increased prevalence of obesity." (PMID 27790107, 2016). "The most substantial effect on BMI-based weight gain from normal to overweight/obesity in adults was observed for the DRD2 variant (rs6277)(OR: 0.79, 95% CI: 0.69–0.90, P = 3.9x10-4, adj." (PMID 26445370, 2015). "DRD2 exhibits effects on weight gain from normal weight to overweight/obesity in adults, while, FTO is associated to weight gain from adolescence to young adulthood." (PMID 26445370, 2015). "DRD2 signaling influences feeding frequency and volume, and mutations in DRD2 are associated with human obesity." (PMID 25183960, 2014). "Several studies in the past decade have shown that in various subject groups the DRD2 gene is associated with alcoholism, drug abuse, smoking, obesity, compulsive gambling, and several personality traits." (PMID 22963930, 2012). "A meta-analysis conducted by Benton and Young (2016), examined the association between the Taq1A polymorphism (rs1800497), located near the DRD2 gene (which encodes the dopamine D2 receptor), and obesity, with implications for the Reward Deficiency Syndrome (RDS) theory." (PMID 40810032, 2025). "In addition, DRD2 polymorphisms are correlates of longitudinal obesity mitigation in Chinese children and adolescents." (PMID 37893019, 2023). "The exaggerated motivation of mice transplanted from obese donors associated with decreased Drd2 expression could reflect the compulsive behavior that is described in the context of obesity." (PMID 37106463, 2023). "Finally, the DRD2 Taq1 A1 allele significantly correlated with other known obesity-related gene variants, such as the OB1875 allele, and this correlation was even stronger in women." (PMID 35954830, 2022).
Obesity (continued). "Predisposition for obesity with nicotine usage may also be associated with genetic risk alleles for obesity, such as the DRD2 A1 variant." (PMID 35954830, 2022). "Some other classes of drugs could be also indirectly involved, such as polymorphism of AT1R associated with hypertension and dopamine receptor D2 variations linked to obesity." (PMID 32477267, 2020). "Although obesity is often associated with dopaminergically active genes (such as in binge eating disorder), in this inquiry, BMI was only associated with expression of DRD2 in our sample within substantia nigra." (PMID 32824878, 2020). "Several lines of evidence suggest obesity-linked genetic risk loci (such as DRD2 and FTO) may influence individual variation in body mass index (BMI) through neuropsychological processes reflected in alterations in activation of the striatum during reward processing." (PMID 29317597, 2018). "The AA genotype reduces dopamine receptor D2 (DRD2) density, promoting increased sugar consumption for neural reward stimulation and thereby elevating obesity risk." (PMID 41340654, 2025). "Dopaminergic genes, including DRD2, ANKK1, OPRM1, COMT, DAT1 and DRD3, especially a polymorphism called Taq1A of DRD2, have been associated with higher reward sensitivity and obesity, which is of significant interest in the effective treatment of BED." (PMID 38613114, 2024). "As the treatment combining DRD1 antagonist SCH23390 and DRD2 agonist quinpirole is effective in ameliorating deficits associated with multiple behaviors in Trappc9-KO mice, we reasoned that this treatment might also be beneficial in controlling obesity or NAFLD in Trappc9-KO mice." (PMID 38889014, 2024). "Subjects with obesity had ~ 2-fold higher protein expression of DRD2 than lean subjects, but DRD1 protein levels only showed a tendency to higher levels in subjects with obesity compared to lean subjects." (PMID 37752366, 2024). "We found that DRD1 and DRD2 gene expression in SAT was up-regulated in subjects with overweight (BMI: 25–29 kg/m2) or subjects with obesity (BMI: ≥30 kg/m2), compared to lean subjects." (PMID 37752366, 2024). "In summary, DRD2 mRNA and protein expression in SAT was associated with hyperglycemia independently of obesity status and increased in subjects with impaired fasting glucose and T2D." (PMID 37752366, 2024). "Taken together, the results in this study suggest that DRD2 protein expression is increased in subjects with obesity, impaired fasting glucose (IFG), and type 2 diabetes (T2D), and positively correlated with hyperglycemia." (PMID 37752366, 2024). "Differences in Drd2 and Adora2 suggest that obesity (specifically, a decrease in ADORA2, which regulates proliferation and reduces apoptosis) causes dysregulation of dopamine signaling." (PMID 39273278, 2024). "Recent data that we published showed a decrease in DRD4 and DRD1 expression with the onset of insulin resistance, while DRD2 expression remained unchanged with the progression of metabolic dysregulation in obesity." (PMID 36768789, 2023). "While the polygenic inheritance of obesity is accepted, one of the most prominent of these genetic risk alleles for RDS is within the DA receptor gene (DRD2), and the Taq1 A1 allele." (PMID 35954830, 2022). "The deficiency of these receptors has been associated with decreased locomotor activity, increased prevalence of obesity, and the modification of the electrophysiological characteristics of DRD2-expressing neurons, among others." (PMID 35564336, 2022). "Single nucleotide polymorphisms of DRD2 and DRD3 have also been associated with obesity, abdominal circumference, triglycerides, HDL cholesterol, and/or glycated hemoglobin in patients with first-episode psychosis." (PMID 35893053, 2022). "Still, our work adds to the growing body of literature on the involvement of DRD2 in weight and obesity, and is in agreement with PET imaging of obese subjects that demonstrated increased D2 availability in substantia nigra." (PMID 32824878, 2020).
Obesity (continued). "Correspondingly, associations between select DRD2 and LEPR allelic gene variations have been associated with the development of severe obesity." (PMID 28588553, 2017). "The variants of the dopamine D2 receptor gene (DRD2) has been found to be associated with alcoholism, drug dependency, obesity, smoking, pathological gambling, ADHD, Tourette syndrome, as well as other related compulsive behaviors." (PMID 24971261, 2013). "In animal models, one study found that rats (both obesity-prone and obesity-resistant rats) increased their intake of high fat food, while, decreasing their intake of “regular” food after receiving bromocriptine (a dopamine, DRD2, agonist)." (PMID 25215200, 2013). "The A1 allele of the DRD2/ANKK1-TaqIA gene has been associated with both addictive disorders and obesity." (PMID 22848508, 2012). "The A1 allele of the DRD2/ANKK1-TaqIA gene has been associated with addictive disorders, with obesity and with the performance in executive functions." (PMID 22848508, 2012). "Conversely, bromocriptine treatment tended to reduce bodyweight and voluntary activity, and reinforce insulin action in DIO mice.These results show that DRD2 activation partly redirects high fat diet induced metabolic anomalies in obesity-prone mice." (PMID 21603181, 2011). "We previously reported an association with the DRD2 TaqI and IVS6-83 variant alleles and the wild-type-239 allele with obesity." (PMID 19183461, 2009). "Finally, polymorphisms in genes such as DRD2 and BDNF have been identified as shared factors associated with both dyslexia and obesity." (PMID 40740817, 2025). "Indeed, the TaqIA allele of the DRD2/ANKK1 gene locus, which results in reduced striatal D2R expression, is associated with increased predisposition to AUD and obesity." (PMID 41015576, 2025). "Notably, this reduction in D2 receptor expression, induced from birth through targeted Drd2 haploinsufficiency in striatal neurons, produced an obesity-like phenotype specifically in male mice." (PMID 41279682, 2025). "mRNA and protein expression of dopamine receptors D1 and D2 (DRD1 and DRD2) were determined in subcutaneous adipose tissue from subjects without or with T2D and with different body weight, and correlated with markers of obesity, hyperglycemia, and insulin resistance." (PMID 37752366, 2024). "Dopamine receptor D2 gene (DRD2) polymorphisms have been associated with cognitive abilities, obesity, addictions, and physical-activity-related behaviors, which may underlie differences in the effectiveness of training programs." (PMID 35564336, 2022). "For example, bradykinesia (slowness of movement) has been attributed to the absence of the murine dopamine D2 receptor gene (Drd2) and to hypothermia, implicated in obesity." (PMID 34574696, 2021). "DRD2 is well known in human and animal models as an actor favouring obesity." (PMID 30621263, 2019). "A meta-analysis has revealed that the genes of pharmacodynamic targets of antipsychotics like HTR2C, DRD2, ADRA2A and genes implicated in obesity such as MC4R, GNB3, FTO, LEP, LEPR, BDNF, and INSIG2 seem to be consistently relevant to antipsychotic-induced weight gain." (PMID 32116676, 2019). "In humans, reduction of striatal D2R expression by the TaqIA allele of the DRD2/Ankyrin repeat and kinase domain containing 1 (ANKK1) gene locus is associated with obesity, while effects of weight loss after bariatric surgery are associated with elevated striatal D2R density." (PMID 27730500, 2017). "Alterations in caudate activation to actual or anticipated receipt of HE palatable food have been linked to genetic variations in the dopamine receptor D2 (DRD2) gene, which is highly expressed in the striatum and linked to increased BMI, familial risk of obesity, and prospective weight gain." (PMID 27169834, 2016).
Obesity (continued). "According to the latest hypothesis, the A1 allele of the DRD2/ANKK1 Taq1A polymorphism is strongly correlated with reduced D2R availability in the striatum, comorbid substance use disorder, obesity, and compulsive behavior." (PMID 25340369, 2014). "However, with further progression of obesity (BMI > 40 kg/m2), the lower tracer BP may reflect primarily a downregulation of DRD2/3, which can be compensatory to long‐term high tonic dopamine exposure." (PMID 37699864, 2023). "Moreover, DRD2 was found to be inversely correlated with the BMI in patients with obesity." (PMID 35369087, 2022). "Positron emission tomography (PET) imaging of individuals with obesity showed reductions in the striatal dopamine receptor type 2 (DRD2) that were proportional to body mass index (BMI), evidence that dopamine deficiency may induce pathological eating as a mechanism to offset the reward circuitry." (PMID 35127598, 2021). "Furthermore, obesity-induced reduction in DRD2 signaling could initiate the following feedback mechanism to further amplify obesity and physical inactivity: obesity → ↓ DRD2 signaling → ↑ physical inactivity → ↑ obesity → futile cycle." (PMID 28588553, 2017). "In addition, polymorphisms in the D2 receptor gene (Drd2) have been linked to obesity and multiple forms of drug addiction." (PMID 24616674, 2014). "We hypothesized, that the presence of DRD2 rs1800497 T and/or DRD4 7R + alleles are more frequent among overweight/obese vs. lean subjects and are associated with weaker reduction of overweight after a 1 year childhood obesity intervention." (PMID 24283216, 2013). "We found that Trappc9-deficient mice presented with systemic glucose homeostatic disturbance, obesity, and NAFLD, which were relieved upon chronic treatment combining dopamine receptor D2 (DRD2) agonist quinpirole and DRD1 antagonist SCH23390." (PMID 38889014, 2024). "Therefore, the finding that individuals carrying genetic variants in DRD2, DRD4, and DAT1 and low MLGP score, associated with a hypofunctional DA system, are related to alterations in cardiometabolic parameters linked to obesity reinforce our results and hypothesis." (PMID 37631349, 2023). "Furthermore, DRD2 plays an important role in mediating glutamatergic neuroplasticity in the striatum (a key component of reward-oriented circuits), and it is precisely to such dopamine-dependent neuroplastic effects that an important role has been attributed in the development of obesity." (PMID 35893053, 2022). "In parallel, the “rs1800497” SNP of the dopamine receptor D2 (DRD2) gene was seen to interlink with the brain–gut microbiota axis and stimulate dysbiosis, negative emotions, and obesity." (PMID 38474710, 2024). "Likewise, functional neuroimaging studies in humans have shown deficiencies in the dopaminergic reward pathways, demonstrating that a decrease in the availability of DRD2 and the DAD4 (DRD4) receptors is determinant for obesity." (PMID 37631349, 2023). "A recent review suggested that the relationship between obesity and DRD2/3 availability can be best described by a nonlinear relationship, where tracer BP reflects changes in both receptor density and endogenous dopamine levels." (PMID 37699864, 2023). "A study in adults undergoing weight-loss treatment programs showed associations between food craving, overeating, and genetic polymorphisms involved in addiction, as well as a significant gene-gene interaction between DRD2 and LEPR, which synergistically influences the development of severe obesity." (PMID 35127598, 2021). "A recent study found that decreased DRD2 signaling in the striatum influences obesity development via reductions in physical activity rather than increases in food intake." (PMID 28588553, 2017).
Obesity (continued). "Since protein levels of DRD1 and DRD2 generally did not follow mRNA expression patterns, we performed correlation analyses between DRD1 and DRD2 protein expression and obesity and hyperglycemia in subjects without T2D and with NGT or IFG, and T2D (cohort 1), respectively." (PMID 37752366, 2024). "These intriguing observations not only suggest a direct link between reduced dopamine function and decreased physical activity, but that the decreases DRD2 signaling can contribute to obesity via reduced energy expenditure rather than the initiation of compulsive overeating." (PMID 28588553, 2017). "Among individuals with the DRD2/ANKK1 haplotype (T-C-T-A) previously associated with obesity, no marked increase in effect of the SLC6A3 VNTR on obesity was observed (** = reference; OR*9 = 0.89, 95% CI 0.54–1.46; OR99 = 0.54, 95% CI 0.23–1.33, p-value for interaction = 0.62)." (PMID 19183461, 2009). "Previously, it has been reported that the DRD2 gene expression does not change in OAT of subjects with obesity and T2D, compared to subjects with obesity but without T2D." (PMID 37752366, 2024). "When considering both subjects without and with T2D, DRD2 protein expression correlated positively with HbA1c (p = 0.029) and AUC glucose during OGTT (p = 0.034), independently of obesity status (respectively)." (PMID 37752366, 2024). "Protein expression of DRD2 in subcutaneous adipose tissue, but not DRD1, is higher in subjects with impaired fasting glucose and T2D and correlated positively with hyperglycemia, HbA1c, and glucose AUC, independent of obesity status." (PMID 37752366, 2024).